FGF23 (fibroblast growth factor 23)
Diseases named in the same sentence as FGF23 in open-access papers (continued):
Sharing a sentence is not in itself a finding about the gene and the disease.
neurofibroma (2 papers, 2020 to 2025). An intraneural or extraneural neoplasm arising from nerve tissues and neural sheaths. "On the other hand, the possibility that a minor amount of FGF23 is synthesized and secreted from neurofibromas cannot be completely excluded yet." (PMID 40133996, 2025). "In this context, a paraneoplastic production of FGF23 by subcutaneous or plexiform neurofibromas has been postulated." (PMID 40133996, 2025).
Obstructive Sleep Apnea (2 papers, 2017 to 2026). "The predictive performance of α-Klotho and FGF-23 for severe obstructive sleep apnea was evaluated using ROC curve analysis." (PMID 41899241, 2026).
ovarian neoplasm (2 papers, 2014 to 2024). A benign, borderline, or malignant neoplasm involving the ovary. "This suggests that elevated FGF23 levels in patients with ovarian tumors indicate advanced-stage disease." (PMID 25181387, 2014).
parathyroid adenoma (2 papers, 2018 to 2019). "Recent research suggests that growth factors, for instance insulin-like growth factor-1 (IGF-1), FGF-23 and vascular endothelial growth factor (VEGF) not only modulate insulin sensitivity but also play a role in the development of parathyroid adenomas and hyperplasia." (PMID 29294178, 2018).
periodontal disease (2 papers, 2023 to 2024). "In conclusion, while biochemical markers such as FGF23, calcium, phosphate, iPTH, creatinine, and urea are essential for managing CKD, they do not predict periodontal disease presence." (PMID 39176315, 2024).
peripheral artery disease (2 papers, 2016 to 2024). "Several reports have pointed out the absence of a relationship between serum FGF23 and atherosclerotic disorders, for instance, arterial calcification, abnormal intima-media thickness, and peripheral artery disease." (PMID 27504998, 2016).
peripheral vascular disease (2 papers, 2014 to 2022). Any disorder affecting blood flow through the veins or arteries outside of the heart. "Whether FGF23 resistance is present among patients with certain cardiac or vascular disorder should be investigated in future studies." (PMID 25200959, 2014).
prediabetes (2 papers, 2021 to 2024). "Patients with early stages of glucose alterations (IR and prediabetes) present higher FGF23 levels compared to normal glucose tolerant subjects." (PMID 34208131, 2021). "The few studies that, together with FGF23, also determine the levels of this protein show that serum αKlotho levels are reduced in patients with prediabetes, although without reaching statistical significance." (PMID 34208131, 2021).
relapsing-remitting MS (2 papers, 2018 to 2021). "Another cohort study including 14 relapsing-remitting MS (RRMS) patients also found that FGF23 concentrations in MS patients were comparable to controls (p = 0.59)." (PMID 34745143, 2021).
renal cell carcinoma (2 papers, 2023 to 2025). "The biosensor was used to determine FGF23 concentrations in the blood plasma of healthy subjects and patients with “clear cell” renal cell carcinoma (ccRCC)." (PMID 37895007, 2023).
renal tubular acidosis (2 papers, 2013 to 2016). A group of genetic disorders of the kidney tubules characterized by the accumulation of metabolically produced acids with elevated plasma chloride, hyperchloremic metabolic acidosis. "Primary de Toni-Debré-Fanconi syndrome is a non-FGF23-mediated hypophosphatemic disorder due to a primary defect in renal proximal tubule cell function resulting in hyperphosphaturia, renal tubular acidosis, glycosuria, and generalized aminoaciduria." (PMID 24386581, 2013).
sarcoma (2 papers, 2023 to 2024). A usually aggressive malignant neoplasm of the soft tissue or bone. "The elevated immunohistochemical expression of FGF23 in undifferentiated pleomorphic sarcoma of the bone suggests that immunohistochemical staining for FGF23 may function as a diagnostic help for this specific type of cancer." (PMID 38397231, 2024). "Approximately 80–90% of undifferentiated pleomorphic sarcoma of the bone (UPSb) tissue sections expressed FGF23 with high intensity." (PMID 38397231, 2024). "Fibroblast Growth Factor 23 (FGF23), expressed explicitly in UPS of the bone compared to other sarcomas, was found to regulate cell proliferation, migration, and angiogenesis." (PMID 36873946, 2023).
Shock (2 papers, 2014 to 2023). The state in which profound and widespread reduction of effective tissue perfusion leads first to reversible, and then if prolonged, to irreversible cellular injury. "In keeping with the experimental observations, patients with cardiogenic shock show a tremendous increase in plasma FGF23 levels, supporting the view that cardiac injury induces rather than follows the elevation of FGF23 levels." (PMID 36977891, 2023).
systemic sclerosis (2 papers, 2018 to 2024). A chronic disorder, possibly autoimmune, marked by excessive production of collagen which results in hardening and thickening of body tissues. "That is why we cannot exclude the participation of these factors in the regulation of the subtle balance between FGF23 and α-Klotho and VD in systemic sclerosis." (PMID 30562918, 2018). "The aim of this study was to assess the simultaneous role of FGF23 and α-Klotho in the development of internal organ involvement in patients with the diffuse type of systemic sclerosis." (PMID 30562918, 2018). "Systemic sclerosis (SSc) is characterized by microvascular damage of skin and internal organs with chronic hypoxia and release of cytokines and hormones such as neutrophil gelatinase-associated lipocalin (NGAL), fibroblast growth factor-23 (FGF-23) and Klotho." (PMID 38777916, 2024). "Our data showed that the FGF23/α-Klotho index may be considered as a novel, potential marker of systemic sclerosis activity." (PMID 30562918, 2018).
type 2 diabetic nephropathy (2 papers, 2013 to 2018). "The present study shows that the kidney of ZDF rats, a model resembling human type 2 diabetic nephropathy, expressed FGF23 starting from the age of 4 months when rats have already significant levels of proteinuria and signs of renal injury." (PMID 23967103, 2013). "Here we investigated whether the kidney was an additional source of FGF23 during renal disease using a model of type 2 diabetic nephropathy." (PMID 23967103, 2013). "We took advantage of the Zucker diabetic fatty (ZDF) rat model of human type 2 diabetic nephropathy characterized by obesity, hyperlipidemia, insulin resistance, progressive renal injury and cardiac abnormalities and evaluated the expression of FGF23 in the kidney during the course of the disease." (PMID 23967103, 2013).
ulcerative colitis (2 papers, 2012 to 2024). An inflammatory bowel disease involving the mucosal surface of the large intestine and rectum. "Regression analysis in the ulcerative colitis group during flare showed the only significant determining factors were FGF23 followed by serum calcium." (PMID 22551310, 2012). "Regression analysis for different clinical and laboratory variables in the ulcerative colitis showed that the only significant determining factors were FGF23 followed by serum calcium." (PMID 22551310, 2012).
Ureteral obstruction (2 papers, 2017 to 2021). Obstruction of the flow of urine through the ureter. "We sought evidence of local renal synthesis in response to unilateral ureteric obstruction in the mouse, and pro-fibrotic actions of FGF23 on the fibroblast in vitro." (PMID 28611350, 2017). "Acute tubulointerstitial injury due to unilateral ureteric obstruction stimulated renal FGF23 synthesis by tubules, and downregulated inactivating proprotein convertases, without effects on systemic mineral metabolism." (PMID 28611350, 2017).
Vitamin D (2 papers, 2023 to 2024). "These therapies target the phosphate and active vitamin D deficiencies consequent to FGF23 excess, rather than addressing the disease-causing elevation in FGF23 itself." (PMID 39539413, 2024).
vitamin deficiency (2 papers, 2025 to 2026). A disorder that is caused by the deficiency of a vitamin. "In our case, the complete and persistent reversal of urine and serum abnormalities upon starting vitamin D replacement helped direct the diagnosis towards vitamin deficiency, rather than FGF-23 independent inherited tubulopathy." (PMID 40225330, 2025).
Acute hepatitis (1 paper, 2024). Acute hepatic injury resulting from inflammation typically accompanied by increased serum alanine transaminase activity. "From a pathophysiological perspective, the major mechanism proposed to explain hepatic FGF23 production in acute hepatitis is inflammation mediated." (PMID 39525686, 2024). "In contrast, we observed a marked increase in FGF23 expression to nearly 60 times normal in acute hepatitis in our mouse model, which also corresponded to the major increases of FGF23 levels observed in our patients in the context of acute hepatitis." (PMID 39525686, 2024). "This translational study raises the hypothesis of renal phosphate wasting induced by excessive hepatic production of FGF23 in case of acute hepatitis." (PMID 39525686, 2024). "This hypothesis is also illustrated in our case by the detection of FGF23 mRNA alongside that of FGF19, the increased expression of which during acute hepatitis is already well established." (PMID 39525686, 2024). "In line with the biochemical parameters described in the case reports, we observed that FGF23 mRNA expression was abundant in liver tissue of the patients with acute hepatitis, moderately detected in cirrhotic liver and not detected in healthy liver." (PMID 39525686, 2024).
acute leukemia (1 paper, 2024). A clonal (malignant) hematopoietic disorder with an acute onset, affecting the bone marrow and the peripheral blood. "As FGF23 suppresses vitamin D synthesis, blood levels of vitamin D drop, and a deficiency in vitamin D is associated with an increased risk of acute leukemia." (PMID 39452542, 2024). "Furthermore, increased plasma concentrations of FGF23 have been found in some hematological malignancies, such as acute leukemia and myelodysplastic syndrome." (PMID 39452542, 2024).
acute myeloid leukemia (1 paper, 2023). Acute myeloid leukemia (AML) is a group of neoplasms arising from precursor cells committed to the myeloid cell-line differentiation. "However, elevated levels of Fgf23 expression, found in our Mov13 mice and which is known to suppress mineralization of osteoblasts and negatively regulate bone homeostasis, are associated with acute myeloid leukemia." (PMID 36967771, 2023).
Airway obstruction (1 paper, 2022). Obstruction of conducting airways of the lung. "We have no data on phosphate concentration in our study meaning that we were unable to assess the relation between FGF-23, phosphate levels, CAD and airway obstruction." (PMID 35263363, 2022).
alcohol-related disorders (1 paper, 2021). Disorders related to or resulting from abuse or mis-use of alcohol. "Recent studies suggest that FGF19, FGF21, and FGF23 are associated with alcohol and alcohol-related disorders." (PMID 34490035, 2021). "Members of fibroblast growth factor (FGF) 19 superfamily, including FGF19, FGF21, and FGF23, are major endocrine mediators that play an important role in alcohol metabolism and alcohol related disorders." (PMID 34490035, 2021).
amyloid cardiomyopathy (1 paper, 2025). "Our finding that FGF-23 levels independently predict cardiac decompensation supports its potential as a mechanistic link between amyloid cardiomyopathy and maladaptive myocardial remodeling." (PMID 41226753, 2025). "In our cohort, FGF-23 correlated not only with glomerular filtration rate (GFR) but also with cardiac biomarkers such as NT-proBNP and hs-TnT, reflecting the cardiorenal interaction in amyloid cardiomyopathy." (PMID 41226753, 2025).
amyotrophic lateral sclerosis (1 paper, 2024). Amyotrophic lateral sclerosis (ALS) is a neurodegenerative disease characterized by progressive muscular paralysis reflecting degeneration of motor neurons in the primary motor cortex, corticospinal tracts, brainstem and spinal cord. "FGF23 expression in skeletal muscle tissue has also been detected in patients with amyotrophic lateral sclerosis (ALS) and in a mouse model of ALS." (PMID 38791164, 2024).
ankylosis (1 paper, 2013). Fixation and immobility of a joint. "In addition to Fgf23, R1MAb2 and vitamin D treatment similarly induced the expression of several genes, including osteocalcin (Ocn), osteoprotegerin (Opg), progressive ankylosis (Ank), dual-specificity phosphatase 6 (Dusp6), and apolipoprotein D (Apod)." (PMID 23451204, 2013).
Anxiety (1 paper, 2020). Intense feelings of nervousness, tension, or panic often arise in response to interpersonal stresses. "Data found diets such as high-protein, low-calorie, low-calorie high-protein diets increased Klotho/FGF23 signaling in the brain, and consequently, Klotho could enhance neuronal plasticity factors and enhance memory and anxiety." (PMID 33072166, 2020).
apical periodontitis (1 paper, 2022). "This highlights the FGF-23 system inflammatory burden caused by apical periodontitis and the positive effect of endodontic treatment on its reduction." (PMID 35888650, 2022).
Ascites (1 paper, 2013). Accumulation of fluid in the peritoneal cavity (between the layers of the peritoneum that lines the abdomen). "On multivariate analysis including FGF23, MELD-Na score and GFR, refractory ascites history and the presence of hepatocarcinoma, only FGF23 plasma concentration remained significantly associated with an increased risk of death (hazard ratio 2.21; 95% CI, 1.69 to 2.92, p<0.001)." (PMID 23825530, 2013).
atrial flutter (1 paper, 2021). A disorder characterized by an electrocardiographic finding of an organized, regular atrial rhythm with atrial rate of 240-340 beats per minute. "Compared to patients in sinus rhythm, both NT-proBNP (p = 0.025) and FGF23 (p < 0.001) were significantly elevated in patients with atrial flutter." (PMID 33534825, 2021).
Atrophy (1 paper, 2019). Any weakening or degeneration, especially through lack of use. "We examined the cross-sectional association between thymic atrophy, evaluated as the number of CD3+CD4+CD45RA+CD31+ cells [recent thymic emigrants (RTE)/μL], and MBD-related factors [(serum PTH, FGF23, and alkaline phosphatase (ALP) level] in 125 patients with non-dialysis dependent CKD." (PMID 30692566, 2019).
B-cell neoplasm (1 paper, 2015). A group of heterogeneous lymphoid tumors generally expressing one or more B-cell antigens or representing malignant transformations of B-lymphocytes. "FGF23 is involved in the regulation of phosphate concentration in plasma, and has been found to be elevated in the serum of patients with B cell neoplasms." (PMID 25765478, 2015).
bacterial sepsis (1 paper, 2024). "Similar clinical data comes from a study of 17 adult patients with CKD and bacterial sepsis, who presented increased proteolysis of the FGF23 peptide at the peak of the bacterial infection, which was reduced after the resolution of the infection." (PMID 39336155, 2024).
bone inflammatory diseases (1 paper, 2022). "The results of this study identify biological targets on which drugs and estrogen may act to control active FGF23 levels in oxidative stress-related bone and non-bone inflammatory diseases." (PMID 35216216, 2022).
Brain atrophy (1 paper, 2022). Partial or complete wasting (loss) of brain tissue that was once present. "Fibroblast growth factor (FGF)-23 (a hormone produced mainly by osteocytes in response to high serum phosphate levels) and Klotho (an obligate coreceptor of FGF-23) were hypothesized to be associated with brain atrophy in AUD." (PMID 35558424, 2022). "Notably, unlike Klotho, they did not observe a significant relationship between FGF-23 levels and brain atrophy in AUD; FGF-23 levels were not inversely related to the bifrontal index." (PMID 35558424, 2022).
Cachexia (1 paper, 2022). Severe weight loss, wasting of muscle, loss of appetite, and general debility related to a chronic disease. "Elevated FGF-23 levels may induce inflammation, leading to protein-energy wasting/cachexia." (PMID 36362179, 2022).
calcium deficiency rickets (1 paper, 2013). "Children with putative dietary calcium deficiency rickets and chronically elevated circulating fibroblast growth factor-23 (FGF23), have been reported in The Gambia." (PMID 23246670, 2013).
cerebral infarction (1 paper, 2024). An ischemic condition of the brain, producing a persistent focal neurological deficit in the area of distribution of the cerebral arteries. "The study found a significant increase in serum Fibroblast Growth Factor-23 (FGF23) levels in patients with Cerebral Infarction (CI) compared to healthy volunteers, (p < 0.001)." (PMID 39096857, 2024). "Based on the study findings, serum FGF23 levels were elevated in patients with Cerebral Infarction (CI) and Vertebral-Basilar Insufficiency (VBI), suggesting the potential use of serum FGF23 levels for diagnosing CI." (PMID 39096857, 2024). "This study aimed to explore the correlation between Fibroblast Growth Factor-23 (FGF23) levels and Cerebral Infarction (CI), and to determine whether there is a significant relationship between FGF23 and the occurrence and severity of CI." (PMID 39096857, 2024). "The study indicates that serum FGF23 level is correlated with vertebrobasilar artery stenosis and may serve as a potential biomarker for diagnosing Cerebral Infarction (CI)." (PMID 39096857, 2024).
childhood cancer (1 paper, 2024). "In conclusion, to the best of our knowledge, this is the first study to investigate the levels of α-Klotho and FGF23 and their association with nephrotoxicity and cardiotoxicity among childhood cancer survivors several years after treatment." (PMID 38792509, 2024).
Cholestatic liver disease (1 paper, 2022). "Our findings demonstrate that the liver produces FGF23 in response to the diverse injuries of a hepatotoxin CCl4, diet-induced fatty liver, and bile acid-induced cholestatic liver disease." (PMID 35231062, 2022).
chondroblastoma (1 paper, 2024). A benign, chondroid-producing, well-circumscribed, lytic neoplasm usually arising from the epiphysis of long bones. "Her FGF23 level returned to normal soon after surgical removal of the tumor, which was confirmed to be chondroblastoma." (PMID 39464221, 2024).
chondromyxoid fibroma (1 paper, 2016). An uncommon benign cartilaginous neoplasm arising from the bone. "FGF23 mRNA expression was detected in all 4 PMTs examined, as well as in 1 chondromyxoid fibroma and 1 myxoid liposarcoma." (PMID 26956379, 2016). "The real-time RT-PCR data showed that the relative expression levels of the FGF23 mRNA tended to be higher in PMTs with TIO than in PMTs without TIO, or in the chondromyxoid fibroma specimen." (PMID 26956379, 2016). "Although RT-PCR testing is highly sensitive, FGF23 mRNA is considered to be structurally normal and could also be detected in non-PMT tumors, including aneurysmal bone cysts and chondromyxoid fibromas." (PMID 26956379, 2016).
chondrosarcoma (1 paper, 2024). A malignant cartilaginous matrix-producing mesenchymal neoplasm arising from the bone and soft tissue. "Although some dedifferentiated chondrosarcoma tissue sections were stained for FGF23, this staining was mild to weak and mainly in the cytoplasm." (PMID 38397231, 2024). "Additionally, weak staining for FGF23 was detectable in the giant cells of dedifferentiated chondrosarcoma." (PMID 38397231, 2024).
chronic allograft nephropathy (1 paper, 2014). "In children with chronic allograft nephropathy, FGF-23 levels increase with the degree of chronic allograft failure, preceding increase in PTH, suggesting that FGF-23 may be a more sensitive biomarker of post-transplant phosphorus dysregulation and continuation or reactivation of CKD–MBD." (PMID 24605319, 2014).